CWC25 (CWC25 spliceosome associated protein)
Description:
Involved in pre-mRNA splicing as component of the spliceosome.
Synonyms: CCDC49; FLJ20291
Tractability: Small molecule: a structure with a bound ligand is known. PROTAC: UniProt records ubiquitination sites on it; its protein half-life has been measured.
Gene: Protein-coding gene on chromosome 17 (38,800,441 to 38,825,646, reverse strand). Ensembl gene ENSG00000273559.
Subcellular location: Nucleus
Subcellular location (Human Protein Atlas): Nuclear speckles
Pathways (Reactome):
Disease: Dengue Virus-Host Interactions
Metabolism of RNA: mRNA Splicing - Major Pathway
Gene Ontology:
Molecular function: protein binding
Biological process: mRNA splicing, via spliceosome
Cellular component: nuclear speck; nucleus; spliceosomal complex; U2-type catalytic step 1 spliceosome; nucleoplasm; U2-type spliceosomal complex
Genetic constraint (gnomAD): Loss-of-function variants: 25 observed, 43.84 expected, observed/expected ratio (o/e) 0.57, 90% interval 0.41 to 0.8. The synonymous counts are far from expectation, so gnomAD's model fits this gene poorly and the ratio says little. Missense variants: 406 observed, 476.14 expected, observed/expected ratio (o/e) 0.85, 90% interval 0.79 to 0.93. Synonymous variants: 135 observed, 176.08 expected, observed/expected ratio (o/e) 0.77, 90% interval 0.67 to 0.88.
Homologues: Orthologues: chimpanzee CWC25 (99% identical), macaque CWC25 (98% identical), pig CWC25 (93% identical), rabbit CWC25 (92% identical), dog CWC25 (90% identical), mouse Cwc25 (89% identical), rat Cwc25 (83% identical), guinea pig CWC25 (77% identical), tropical clawed frog cwc25 (61% identical), zebrafish cwc25 (54% identical), Drosophila melanogaster Cwc25 (37% identical), Caenorhabditis elegans mog-3 (25% identical).
Diseases named in the same sentence as CWC25 in open-access papers:
CWC25 is named in the same sentence as 2 diseases in open-access papers, as found by Europe PMC text mining. Sharing a sentence is not in itself a finding about the gene and the disease. The quoted sentences say what the papers report.
breast carcinoma (2 papers, 2014 to 2022). "Few studies have shown the prognostic value of CBWD1, CWC25, IFNA2, KRT27, or ZDHHC21 in breast cancer, and subsequent studies are expected." (PMID 36077687, 2022).
cancer (1 paper, 2023). A tumor composed of atypical neoplastic, often pleomorphic cells that invade other tissues. "With respect to genes CDK12 (CRKRS), CWC25 (CCDC49), GRB7, MIEN1 (C17orf37), PNMT and SIRT3, they have been shown to be linked to HER2 receptor and cancer." (PMID 37096121, 2023).